MTOR (mechanistic target of rapamycin kinase)
Diseases named in the same sentence as MTOR in open-access papers (continued):
Sharing a sentence is not in itself a finding about the gene and the disease.
pancreatic cancer (continued). "We further provided evidence that dual mTOR inhibitor AZD8055 significantly reversed the aberrant mTOR activation, consequently sensitized pancreatic cancer cell lines and xenografts to radiotherapy." (PMID 23886294, 2013). "In combination with other agents, the blockage of PI3K/mTOR pathway in pancreatic cancer was able to eliminate pancreatic CSCs and leukemia stem cells, demonstrating the anti-CSC efficacy of inhibiting the PI3K/mTOR pathway." (PMID 23826249, 2013). "We propose that mTOR play a critical role in radioresistance and its dual inhibitor AZD8055 can be used in combination with radiation to overcome the radioresistance in pancreatic cancer treatment." (PMID 23886294, 2013). "The major signal transduction pathways in pancreatic cancer pathogenesis and progression are RAS/mitogen-activated protein kinase (MAPK), phosphatidylinositol 3-kinase (PI3K)/Akt/mTOR, and hedgehog pathways." (PMID 24212624, 2011). "Silencing of Akt or mTOR with gene specific-siRNA sensitized the pancreatic cancer cells to CDDO-Me, demonstrating Akt and mTOR as molecular targets of CDDO-Me for its growth inhibitory and apoptosis-inducing activity." (PMID 21799944, 2010). "The aim of this study was to investigate the effect of epidermal growth factor on the expression of HCCR in pancreatic cancer cells, and to explore if PI3K/Akt/mTOR signaling pathway mediated this expression." (PMID 20423485, 2010). "Studies demonstrate that radiation enhances glycolysis in pancreatic cancer cells, raising lactate levels and promoting MDSC activity via the GPR81/mTOR/HIF-1A/STAT3 pathways, thus contributing to an immunosuppressive microenvironment and tumor progression, recurrence, and radioresistance." (PMID 41424847, 2026). "And in murine models of pancreatic cancer, IL-18-induced activation of the PI3K-Akt/mTOR pathway leads to the exhaustion of intratumoral CD8+ T cells, suggesting that mTOR inhibition mediated by DDIT4 may potentially ameliorate this process." (PMID 40900790, 2025). "For example, in pancreatic cancer, ALKBH1 functions as a demethylase of m1A modification, participating in the occurrence and development of pancreatic cancer through the mTOR and ErbB signalling pathways, and its low expression is related to the poor prognosis of patients." (PMID 41017026, 2025). "Likewise, in pancreatic cancer cells (PANC-1, AsPC-1, BxPC-3), TQ downregulates HIF-1α via PI3K/AKT/mTOR inhibition and enhanced ubiquitination." (PMID 41303508, 2025). "Therefore, we reveal that CuB can induce cellular mitophagy, inhibit glycolysis in pancreatic cancer cells, and improve the TME in terms of metabolic balance through the PI3K/Akt/mTOR and PINK1/Parkin pathways and LDHA downregulation." (PMID 40944197, 2025). "Anti‐pancreatic cancer cell assays demonstrated that PVP3‐1‐Se0NPs effectively inhibited the proliferation and migration of pancreatic cancer cells in vitro, inducing apoptosis and autophagy in cancer cells by inhibiting the mTOR signaling pathway." (PMID 40951588, 2025). "The PI3K/Akt/mTOR pathway is essential in the physiology and pathology of PDAC, and its excessive activation has been reported in nearly all solid tumors, including pancreatic cancer." (PMID 39458993, 2024). "In our study, we found that silencing of HHLA2 can inhibit the EMT process of pancreatic cancer cells, and the mechanism may be related to the regulation of EGFR/MAPK /mTOR/AKT/ERK1/2 signaling pathway." (PMID 38762741, 2024). "Through in vivo and in vitro experiments, we revealed that MSI2 directly binds to the NLK mRNA to maintain its stability and promote the invasion and migration of pancreatic cancer cells, and NLK promotes pancreatic cancer progression through the EMT and PI3K/AKT/mTOR signaling pathway." (PMID 39097735, 2024). "However, further research is required to elucidate the complex molecular interactions between the Akt-mTOR and PKA-Hippo-YAP pathways in the context of Gαi3-driven pancreatic cancer progression." (PMID 39349432, 2024).
pancreatic cancer (continued). "The regulation of PI3K/AKT/mTOR signaling by MSI2 and NLK in pancreatic cancer is still unclear." (PMID 39097735, 2024). "PI3K/Akt/mTOR axis has already been established to play an essential role in CSC biology and mTOR inhibitors have been proved to eradicate CSCs in different human cancers (neuroblastoma, nasopharyngeal, colon, and pancreatic cancers)." (PMID 37685983, 2023). "Our study establishes the effect of mTOR inhibitor Rapamycin on translation programs in pancreatic cancer lacking 4EBP1 expression." (PMID 36900235, 2023). "The PI3K/AKT/mTOR (phosphatidylinositol 3-kinase/protein kinase B/mammalian target of rapamycin) pathway can be initiated by PROK1 (prokineticin 1), but its effect and mechanism of action in pancreatic carcinoma (PC) are not fully understood." (PMID 37070074, 2023). "Targeting insulin receptors and downstream factors such as PI3K, mTOR, HIF-1 may help us inhibit tumor progression and restore drug sensitivity in pancreatic cancer." (PMID 35252207, 2022). "The activation of the mTOR signaling pathway and the autocrine of NGF may together promote the invasion and migration ability of pancreatic cancer cells." (PMID 35449152, 2022). "As a downstream molecule of mTOR, ERAP2 inhibition may have better potential for pancreatic cancer treatment and blockade of gemcitabine resistance." (PMID 36214762, 2022). "Most importantly, we uncovered the significance of ATF4/TXNIP/REDD1/mTOR signaling in the control of the biological activities of GW3965, which was corroborated by expressional analysis on xenograft tumor samples as well as human tissues of pancreatic cancer." (PMID 38089448, 2022). "Furthermore, hypoxia-induced NR2F1-AS1 expression directly augmented NR2F1 levels to favor pancreatic cancer cell migration and invasion through up-regulating AKT/mTOR signaling." (PMID 36230565, 2022). "In addition, the interaction of rapamycin kinase (mTOR) mechanism target signal and glutathione peroxidase 4 (GPX4) signal can regulate autophagy-dependent ferroptosis in human pancreatic cancer cells." (PMID 35057861, 2022). "The effect of Evr and/or mTOR overexpression or GEM on cell viability, migration, apoptosis, and glucose metabolism (Warburg effect) was evaluated in GEM-sensitive (GEMsen) and GEM-resistant (GEMres) pancreatic cancer cells." (PMID 33849427, 2021). "Finally, the effects of PI3K–Akt signaling pathway inhibitors (mTOR inhibitor, GSK2126458) on cell viability of pancreatic cancer cells were detected by MTT, colony and invasion assays." (PMID 34461940, 2021). "Next, we explored whether activation of PI3K-Akt-mTOR and Notch signaling pathways contributed to the pro-proliferation and anti-apoptotic functions of KLK8 in pancreatic cancer cells." (PMID 34395235, 2021). "Interestingly, in pancreatic cancer cells, overexpression of HNF1A activated PTEN protein, thereby preventing AKT/mTOR phosphorylation and cell proliferation." (PMID 34234870, 2021). "Multiple signaling pathways and downstream proteins such as phosphatidylinositol-4,5-bisphosphate 3-kinase/protein kinase B/mammalian target of rapamycin (PI3K/AKT/mTOR), nuclear factor-κB, and mitogen-activated protein kinases are involved in GEM resistance in pancreatic cancer." (PMID 33849427, 2021). "The expression of mTOR signaling channel proteins was detected using western blotting to investigate the potential mechanisms of CC-223, NSC781406, and BGT226 inhibitors on pancreatic cancer." (PMID 33343350, 2020).
pancreatic cancer (continued). "Similarly, alisertib (ALS), a potent and selective Aurora kinase A inhibitor, induces cell cycle arrest and autophagy and suppresses EMT involving PI3K/Akt/mTOR and SIRT1-mediated signaling pathways in human pancreatic cancer cells." (PMID 33042011, 2020). "This indicates that the inhibition of pancreatic cancer cells by betulinic acid is through the targeting of mTOR signaling, rather than Nrf2 or JAK2." (PMID 32513155, 2020). "We speculated that betulinic acid may inhibit the proliferation and apoptosis of pancreatic cancer cells by promoting the activation of AMPK, inhibiting the activation of mTOR, as well as inducing autophagy and inhibiting protein synthesis." (PMID 32513155, 2020). "In light of our previous study suggesting that PBI-05204 down-regulated PI3K/Akt/mTOR pathway in pancreatic cancer and that this particular network is activated in almost 90% of GBM patients, we first examined the expression of PI3K/Akt/mTOR signaling proteins in PBI-05204–treated U87MG cells." (PMID 33013390, 2020). "We also determined that betulinic acid inhibited pancreatic cancer by specifically targeting mTOR signaling rather than Nrf2 or JAK2." (PMID 32513155, 2020). "Overall, our findings suggest that for tumours of the two major pancreatic cancer subtypes, oncogenesis may be primarily driven by perturbation in either SMAD4 or mTOR signalling." (PMID 31988390, 2020). "Interestingly, chemoresistance was observed in pancreatic cancer cells treated with CXCL12-α and, subsequently, with mTOR-targeted therapies or gemcitabine." (PMID 31275385, 2019). "Three datasets closely related to the Warburg effect (glycolysis, PI3K/AKT/mTOR signaling, and mTORC1 signaling) were enriched in the NFAT5 high-expression group, indicating that NFAT5 may have an impact on glucose metabolism in pancreatic cancer." (PMID 31827081, 2019). "In breast and pancreatic cancer cells, FAK is assumed to act up-stream of the Wnt/β-catenin pathway, while in other systems, FAK acts downstream of Wnt promoting AKT/mTOR activation in vivo and leading to increased intestinal cell proliferation and tumorigenesis." (PMID 31671889, 2019). "Mechanistically, LAT2 could regulate the glutamine/p-mTORSer2448/glutamine synthetase feedback loop to keep mTOR activated and to upregulate LDHB in order to activate glycolysis, thereby promoting chemoresistance in pancreatic cancer cells." (PMID 30419950, 2018). "Similarly, combined mTOR and HDAC inhibition were reported to exert synergistic anti-tumor activity in models of breast and pancreatic cancer and NSCLC." (PMID 29389967, 2018). "Taken together, our data reveal that LAT2 functions as an oncogenic protein and could regulate glutamine-dependent mTOR activation to promote glycolysis and decrease GEM sensitivity in pancreatic cancer." (PMID 30419950, 2018). "It has been reported in the literature that α-solanine acts as an antitumor agent in inhibition of Wnt/β-catenin, Akt/mTOR, Stat3 and NF-κB pathways in non-toxic concentrations in healthy cells and in pancreatic cancer cells (PANC-1)." (PMID 29799481, 2018). "Thus, it was concluded that the combination forbids gemcitabine sensitivity and induces apoptosis in pancreatic cancer cells by avoiding Notch1/PTEN, PI3K/Akt/mTOR, NF-κB pathways." (PMID 29311925, 2017). "SCH772984 potentiates the cytotoxic effect of CuB on pancreatic cancer cells through complementary inhibition of EGFR, PI3K/Akt/mTOR, STAT3 and ERK signaling, followed by an increase in the pro-apoptotic protein Bim and a decrease in the anti-apoptotic proteins Mcl-1, Bcl-2, Bcl-xl and survivin." (PMID 29262554, 2017). "In addition, evodiamine, which targets AKT1 and PI3K, PKA, mTOR and PTEN sensitizes pancreatic cancer cells to gemcitabine." (PMID 29023490, 2017).
pancreatic cancer (continued). "Therefore, our studies suggested that PDGFRα and KIT downregulation in pancreatic cancer leads to decreased p70S6K phosphorylation at Ser 418, and increased IRS-1 phosphorylation at Ser 636 via increased PI3K/AKT mTOR/P70S6K signaling." (PMID 27014871, 2016). "As mTOR activation is reported to be the hall mark of several cancers, DEPTOR in general should act as tumor suppressor and its expression was reported to have growth suppression effects in pancreatic cancer cells." (PMID 26992219, 2016). "Furthermore, SOM230 was shown to be at least as potent as the mTORC1 (RAD001) and mTOR (PP242) inhibitors at suppressing protein synthesis and re-sensitizing pancreatic cancer cells to gemcitabine cytotoxicity." (PMID 25834145, 2015). "Other studies in pancreatic cancer also favor combinations with PI3-kinase and mTOR inhibitors." (PMID 25803170, 2015). "Differentially expressed KEGG pathways between high- and low-risk patients included cancer cell signaling pathways (MAPK, VEGF, MTOR, and ERBB signaling pathways) and cancer pathways (acute myeloid leukemia, non-small cell lung cancer, chronic myeloid leukemia, and pancreatic cancer)." (PMID 25180633, 2014). "The central role of the mammalian target of rapamycin (mTOR) in mediating a crosstalk between the insulin/IGF-1 and GPCR signaling in pancreatic cancer cells is discussed in depth and strategies, including the use of metformin, to target this signaling pathway in PDAC cells are proposed." (PMID 25540626, 2014). "Thus, CHIP can negatively regulate PI3K/AKT/mTOR and Src/FAK/paxillin pathway activation in pancreatic cancer cells." (PMID 24722501, 2014). "Currently mTOR is considered as one of the potential alternative targets for PDAC treatment and is also considered as a master regulator similar to what we show here for IGF-1R in pancreatic cancer." (PMID 24809702, 2014). "This article highlights the central role of the mechanistic target of rapamycin (mTOR) in mediating crosstalk between insulin/IGF-1 and GPCR signaling in pancreatic cancer cells and proposes strategies, including the use of metformin, to target this signaling system in PDAC cells." (PMID 25295009, 2014). "Altogether, our data suggest that blockade of mTOR signal pathway by AZD8055 could reverse radioresistance and sensitize pancreatic cancer cells to ionizing radiation." (PMID 23886294, 2013). "We have shown previously that sphere cultures of pancreatic cancer cells enrich for cancer stem cells, and that combined targeting of the Sonic Hedgehog (SHH) and mTOR pathways may offer a new therapeutic option." (PMID 23825539, 2013). "Our results add LPAAT-β to the list of PA generating enzymes involved in mTOR signaling and provide further evidence that LPAAT-β is a potential tumor-promoting protein, and validate LPAAT-β as a molecular target for drug discovery in pancreatic cancer." (PMID 24205284, 2013). "Together, these data suggest that the inhibition of antiapoptotic Akt, mTOR and NF-κB might be necessary for induction of apoptosis by CDDO-Me in pancreatic cancer cells." (PMID 21799944, 2010). "The inhibition of Akt/mTOR signaling pathway and its downstream intermediates suggested that the inhibition of these antiapoptotic proteins is critical for the induction of apoptosis by CDDO-Me in pancreatic cancer cells." (PMID 21799944, 2010). "It is therefore conceivable that IRS-Ser612 is a mTOR-regulated site that is part of a negative feedback loop, and that mTOR inhibitors enhance pAkt levels in pancreatic cancer cells by blocking its phosphorylation." (PMID 20630061, 2010). "We determined whether induction of apoptosis in pancreatic cancer cells by CDDO-Me involved inhibition of Akt, mTOR and NF-κB." (PMID 21799944, 2010). "Thus, these experiments showed that Akt and mTOR are major targets of CDDO-Me for suppressing growth and inducing apoptosis in pancreatic cancer cells." (PMID 21799944, 2010).
pancreatic cancer (continued). "For instance, HIF‐1α induced NR2F1‐AS1 upregulation in pancreatic cancer (PC) and highly expressed NR2F1‐AS1 promoted PC cell proliferation, migration, and invasion by modulating the expression of its sense gene NR2F1, which activates the AKT/mTOR pathway in PC." (PMID 39224045, 2024). "mTOR inhibition alone is not sufficient for the treatment of pancreatic cancer." (PMID 38675189, 2024). "In pancreatic cancer cells, however, not only was AMPK level or its activation (p‐AMPK) altered by GW3965 treatment but knocking down AMPK by siRNA did not affect REDD1 level in response to GW3965, suggesting the specificity of ATF4 and TXNIP in regulating REDD1 and mTOR in these cancer cells." (PMID 38089448, 2022). "Moreover, knocking down PES1 increased the sensitivity of pancreatic cancer cells to BET inhibitors, AKT inhibitors and mTOR pathway inhibitors, and decreased the mRNA and protein levels of c-Myc, which is related to the sensitivity of pancreatic cancer cells to BET inhibitors." (PMID 34976188, 2022). "Thus, blocking the HGF/c-Met/mTOR signaling pathway can inhibit cancer cells invading and migrating along nerves and may be a therapeutic target for PNI in pancreatic cancer." (PMID 35449152, 2022). "Furthermore, we established that fisetin repressed pancreatic cancer via explicitly targeting PI3K/AKT/mTOR signaling cascade and not the JAK2 cascade." (PMID 34821587, 2021). "Besides these effects, mTOR activity–dependent alterations can induce protein expression (e.g., that of BMP2 and Sestrin2) and promote EMT and metastasis in different cancer models (ovarian, nasopharyngeal, pancreatic cancer, NSCLC, and HCC)." (PMID 35029792, 2021). "Here, we show that benproperine phosphate (BPP), a cough suppressant, triggers AMPK/mTOR‐mediated autophagy initiation and disturbs Ras‐related protein Rab‐11A (RAB11A)‐mediated autophagosome–lysosome fusion, resulting in excessive accumulation of autophagosomes in pancreatic cancer (PC) cells." (PMID 33226737, 2021). "Our data implicate that hypoxia-induced FUT11 contributes to proliferation and metastasis of PC by maintaining the stability of PDK1, thus mediating activation of AKT/mTOR signaling pathway, and suggest that FUT11 could be a novel and effective target for the treatment of pancreatic cancer." (PMID 34221996, 2021). "The radiosensitising properties of PI3K/AKT/mTOR inhibitors have also been demonstrated in soft tissue sarcoma, bladder transitional cell carcinoma, hepatocellular carcinoma, metastatic renal cell carcinoma Burkitt’s lymphoma, SCC of the cervix and pancreatic cancer." (PMID 32443649, 2020). "Furthermore, we explored the potential mechanism by which betulinic acid inhibited pancreatic cancer, and found that betulinic acid induces apoptosis by specifically through targeting mTOR signaling rather than Nrf2 or JAK2." (PMID 32513155, 2020). "Bovine seminal RNase (BS-RNase) triggers an autophagic cell death process in pancreatic cancer cells mediated by BECN1 induction; and onconase, a RNaseA superfamily member proposed for chemotherapy, inhibits the proliferation of cancer cells through the ROS/Akt/mTOR pathway." (PMID 31312205, 2019). "As HSP90 expression is regulated by PI3K/AKT/mTOR axis, we next evaluated whether the activation of mTOR complexes (mTORC1 and mTORC2) could correlate with expression of HSP90 in Apigenin-treated pancreatic cancer cells." (PMID 31121848, 2019). "Treating cells with Rapamycin, a specific inhibitor of mTOR, showed a decrease in the proliferation and viability of the entire glial cell populations, including stem/progenitor cells: the percentage of CD133+ cells remained after treatment in pancreatic cancers." (PMID 30323898, 2018). "Moreover, the KEGG analysis found that a variety of signaling pathways such as AMPK, mTOR and PI3K/Akt, which may regulate the stemness of pancreatic cancer cells, were enriched after gemcitabine exposure." (PMID 29018223, 2017).